SP4 (Sp4 transcription factor)
Description:
Binds to GT and GC boxes promoters elements. Probable transcriptional activator.
Synonyms: SPR-1; HF1B; MGC130008; MGC130009
Tractability: PROTAC: its protein half-life has been measured.
Gene: Protein-coding gene on chromosome 7 (21,428,043 to 21,514,822, forward strand). Ensembl gene ENSG00000105866.
Subcellular location: Nucleus
Subcellular location (Human Protein Atlas): Nucleoplasm; Cytosol
Gene Ontology:
Molecular function: identical protein binding; protein binding; sequence-specific DNA binding; DNA-binding transcription factor activity, RNA polymerase II-specific; RNA polymerase II cis-regulatory region sequence-specific DNA binding
Biological process: regulation of transcription by RNA polymerase II
Cellular component: nucleoplasm; chromatin; nucleus
Genetic constraint (gnomAD): Loss-of-function variants: 15 observed, 68.13 expected, observed/expected ratio (o/e) 0.22, 90% interval 0.15 to 0.34. The upper end of that interval is the gene's LOEUF score, 0.34, which puts it in group 1 of 6, group 1 being the genes least tolerant of losing a copy. Missense variants: 999 observed, 956.91 expected, observed/expected ratio (o/e) 1.04, 90% interval 0.99 to 1.1. Synonymous variants: 394 observed, 346.47 expected, observed/expected ratio (o/e) 1.14, 90% interval 1.05 to 1.24.
Homologues: Orthologues: chimpanzee SP4 (100% identical), macaque SP4 (99% identical), dog SP4 (98% identical), guinea pig SP4 (98% identical), mouse Sp4 (97% identical), rabbit SP4 (97% identical), rat Sp4 (97% identical), tropical clawed frog sp4 (82% identical), pig SP4 (74% identical), zebrafish sp4 (60% identical). Paralogues in human: SP1 (41% identical), SP3 (38% identical), SP2 (31% identical).
Diseases named in the same sentence as SP4 in open-access papers:
SP4 is named in the same sentence as 66 diseases in open-access papers, as found by Europe PMC text mining. Sharing a sentence is not in itself a finding about the gene and the disease. The quoted sentences say what the papers report.
schizophrenia (19 papers, 2009 to 2026). A major psychotic disorder characterized by abnormalities in the perception or expression of reality. "We meta-analyzed large-scale brain transcriptomic data from mice harboring individual loss-of-function mutations in seven schizophrenia risk genes (Akap11, Dagla, Gria3, Grin2a, Sp4, Srrm2, Zmym2)." (PMID 41022686, 2025). "GRIN2A is one of only two genes in the genome that have been linked to schizophrenia through both rare loss-of-function genetic variation and common genetic variation, and the other gene, SP4, encodes a transcription factor that regulates GRIN2A expression." (PMID 40701976, 2025). "Specifically, SP4 has been associated with improvements in symptoms in women with schizophrenia treated with raloxifene." (PMID 38919799, 2024). "Among these top ten risk genes, truncation of the SP4 gene has an odds ratio of 9.37 (3.38–29.7) for schizophrenia." (PMID 34750502, 2022). "By taking advantage of the specific localization of the GC-boxes bound by SP4 transcription factors, I analyzed the relative abundance of these GC-boxes in the proximal promoter regions of schizophrenia-risk genes." (PMID 34750502, 2022). "The frequency of the GC-boxes peaks at the proximal promoter region (−140,−41) where Sp4 binds to activate gene expression in schizophrenia-risk genes." (PMID 34750502, 2022). "Does Sp4 control the expression of many of these schizophrenia-risk genes via the GC-boxes in their proximal promoter regions in neuronal cells, given that the GC-box can be readily found in the 5ʹ-regulatory regions of a variety of genes?" (PMID 34750502, 2022). "Recent human genetic studies from both the Schizophrenia Exome Sequencing Meta-Analysis (SCHEMA) and the Genome-Wide Association Study (GWAS) validated SP4 as a schizophrenia-risk gene over the exome-wide or the genome-wide significance." (PMID 34750502, 2022). "SP4, a transcription factor targeting GC-rich sequences around the promoters of numerous genes, was found to be associated with schizophrenia, bipolar disorder and major depression." (PMID 29513708, 2018). "Genetic variations at the human SP4 locus have been associated with bipolar disorder and schizophrenia." (PMID 25915526, 2015). "Several human genetic studies suggested the association of SP4 gene with schizophrenia and other psychiatric disorders." (PMID 23823008, 2013). "Human SP4 gene was found to be deleted in schizophrenia, and its SNPs have been reported to associate with bipolar, schizophrenia, and major depression." (PMID 23823008, 2013). "Taken together, the pharmacological studies on Sp4 hypomorphic mice provided additional support for SP4 gene as a susceptibility gene for bipolar disorder and schizophrenia." (PMID 19401786, 2009). "Both human genetic and mouse pharmacogenetic studies support Sp4 gene as a susceptibility gene for bipolar disorder or schizophrenia." (PMID 19401786, 2009). "Our human genetic association studies provide direct evidence for the human SP4 gene as a susceptibility gene for both bipolar disorder and schizophrenia." (PMID 19401786, 2009). "We selected ten single nucleotide polymorphisms (SNPs) encompassing the human SP4 genomic locus, and examined their association with both bipolar disorder and schizophrenia in European and Chinese Han populations, respectively." (PMID 19401786, 2009). "All together, we observed a significant genetic association between human SP4 gene and bipolar disorder and schizophrenia in all three independent samples." (PMID 19401786, 2009). "The human SP4 gene is therefore examined for its association with both bipolar disorder and schizophrenia in European Caucasian and Chinese populations respectively." (PMID 19401786, 2009). "Significant associations were observed between SP4 gene and bipolar disorder/schizophrenia in all three independent samples." (PMID 19401786, 2009).
schizophrenia (continued). "On the other hand, the human SP4 gene has been mapped to chromosome 7p15, where a susceptibility locus was suggested for a broad spectrum of human psychiatric disorders, including schizophrenia, panic disorder, ADHD, autism, and bipolar disorder." (PMID 19401786, 2009). "After conducting genetic association studies, we observed a significant association between the human SP4 gene and bipolar disorder and schizophrenia in all three independent samples." (PMID 19401786, 2009). "Sp4, which encodes a transcription factor, has additionally been genetically linked to schizophrenia through GWAS fine-mapping, and may also be genetically associated with bipolar disorder (BP)." (PMID 41022686, 2025). "Moreover, two genes, GRIN2A and SP4, were prioritised as credible causal candidates in the most recent large schizophrenia GWAS4." (PMID 40753099, 2025). "Whether a specific GC-box in a schizophrenia-risk gene is bound by Sp4 may also depend on neuronal cell types, and has to be determined by experiments such as chromatin immunoprecipitation and sequencing (ChIP-seq)." (PMID 34750502, 2022). "Indeed, GRIN2A and SP4, 2 genes implicated in schizophrenia susceptibility through both fine-mapping of GWAS loci and exome sequencing, have direct roles in NMDA receptor function and associative memory." (PMID 34974922, 2022). "Such a Sp4-controlled network of different schizophrenia-risk genes may contribute to the over-representation of the GC-box containing genes." (PMID 34750502, 2022). "Moreover, human SP4 gene single nucleotide polymorphisms (SNPs) were also reported to associate with bipolar disorder, schizophrenia, and major depression." (PMID 23823008, 2013). "Taken together, these data provide strong support for the hypothesis that the SP4 gene functions as a susceptibility gene for bipolar disorder and possibly for schizophrenia as well, since the two disorders have overlapping genetic components." (PMID 19401786, 2009). "Association analysis of SP4 gene with both bipolar disorder and schizophrenia." (PMID 19401786, 2009). "To explore whether SP4 gene might also be associated with schizophrenia, we conducted genetic studies on a sample of 325 Chinese trio families with schizophrenia." (PMID 19401786, 2009). "Considering deficient sensorimotor gating in Sp4 hypomorphic mice and human SP4 gene localized in a susceptibility locus for bipolar disorder, we therefore examined whether human SP4 gene may associate with bipolar disorder and schizophrenia." (PMID 19401786, 2009). "SP4 is involved in the development of dendritic trees in brain and hippocampal granule neurons, suggesting that SP4 might be linked to schizophrenia in the context of the theory of neurodevelopment." (PMID 38919799, 2024). "Nine genes are robustly associated with schizophrenia through deleterious mutations in these genes: SETD1A, CUL1, XPO7, TRIOCANCA1G, SP4, GRIA3, GRIN2A, and HERC1." (PMID 38911007, 2022). "Reduction of Sp4 expression causes age-dependent hippocampal vacuolization and many other intermediate phenotypes of schizophrenia in Sp4 hypomorphic mice." (PMID 34750502, 2022). "Out of the top ten high-risk genes, Sp4 and RB1CC1, the only two DNA-binding transcription factors, bind the same GC-box in regulation of genes involved in the pathogenesis of schizophrenia." (PMID 34750502, 2022). "In previous studies, Sp4 has been shown to be important in regulating gamma-aminobutyric acid-ergic (GABAergic) neurons, and has been correlated with the occurrence of schizophrenia." (PMID 31717924, 2019). "SP4 gene was also reported to be sporadically deleted in schizophrenia patients and had reduced expression in postmortem brains of bipolar patients." (PMID 29513708, 2018). "We have recently described an increase in SP4 phosphorylation in the postmortem cerebellum of bipolar disorder and schizophrenia patients." (PMID 25915526, 2015).
schizophrenia (continued). "Altered expression of transcription factor specificity protein 4 (SP4) has been found in the postmortem brain of patients with psychiatric disorders including schizophrenia and bipolar disorder." (PMID 25915526, 2015). "In the present work, we report that Sp4 hypomorphic mice also exhibit prolonged responses to NMDAR antagonists germane to Luby’s striking findings in schizophrenia more than 50 years ago." (PMID 23823008, 2013). "We previously reported that Sp4 hypomorphic mice displayed several putative endophenotypes for schizophrenia and other psychiatric disorders." (PMID 23823008, 2013). "Together, these data demonstrated Sp4 hypomorphic mice as a promising hypoglutamatergic model for schizophrenia." (PMID 23823008, 2013). "On the other hand, we found a gene dosage effect for mouse Sp4 gene in the modulation of sensorimotor gating, a putative endophenotype for both schizophrenia and bipolar disorder." (PMID 19401786, 2009). "Unlike the GC-boxes, however, there is no over-representation of the GA-box containing genes within the schizophrenia-risk genes likely due to lack of selective pressure for the GA-boxes by Sp4 and other possible transcription factors." (PMID 34750502, 2022). "In the brain, Sp4 and a majority of other schizophrenia-risk genes are specifically expressed in neurons, but not glia." (PMID 34750502, 2022). "Truncation of the human SP4 gene has an odds ratio of 9.37 (3.38–29.7) for schizophrenia." (PMID 34750502, 2022). "Interestingly, RB1CC1 binds the same GC-box sequence GGGCGG but more upstream of TSS than Sp4, highlighting the importance of the GC-box in the regulation of genes involved in the pathogenesis of schizophrenia." (PMID 34750502, 2022). "In addition, previous studies have shown altered SP4 protein abundance in the postmortem cerebellum and prefrontal cortex both in bipolar disorder and schizophrenia, as well as in the hippocampus in schizophrenia." (PMID 25915526, 2015). "We developed a new method for multi-channel epidural ERP characterization in behaving mice with high precision, reliability and convenience and report an application to time-domain ERP feature characterization of the Sp4 hypomorphic mouse model for schizophrenia." (PMID 26459883, 2015). "Importantly, human SP4 gene was found to be deleted in schizophrenia 20,21, and its expression was decreased in the postmortem brains of bipolar patients." (PMID 23823008, 2013). "On the other hand, human SP4 gene was reported to be deleted in schizophrenia." (PMID 23823008, 2013). "Excessive dopamine transmission has been proposed in the pathophysiology of both bipolar disorder and schizophrenia; we therefore examined whether similar disruption of dopamine neurotransmission occurred in hypomorphic Sp4 mice." (PMID 19401786, 2009). "However, decreased expression of human SP1 gene, functionally redundant with its family member SP4 gene, was reported in the prefrontal cortex and striatum of postmortem brains of schizophrenia patients." (PMID 19401786, 2009). "However, the expression of human SP1 gene, which functionally substitutes with SP4 gene by recognizing the same DNA binding motif, was found to be reduced in both prefrontal cortex and striatum of postmortem brains of schizophrenia patients." (PMID 19401786, 2009). "Consistent with the reduced expression of SP1 gene in schizophrenia, reduced expression of mouse Sp4 gene resulted in both hippocampal abnormalities and deficient sensorimotor gating, two putative endophenotypes for schizophrenia and related psychiatric disorders." (PMID 19401786, 2009). "In contrast to Sp1/Sp4 transcription factors that recognize the GC-boxes in the proximal promoter region (−140,−41), the GC-boxes more upstream of this region can be bound by other transcription factors such as RB1CC1, another high-risk gene for schizophrenia from the SCHEMA." (PMID 34750502, 2022).
schizophrenia (continued). "Reduced expression of Sp4, the murine homolog of human SP4, a risk gene of multiple psychiatric disorders, led to N-methyl-D-aspartate (NMDA) hypofunction in mice, producing behavioral phenotypes reminiscent of schizophrenia, including hypersensitivity to ketamine." (PMID 29513708, 2018). "Therefore, elucidation of the Sp4 molecular pathway in Sp4 hypomorphic mice may provide novel insights to our understanding of abnormal NMDAR signaling in schizophrenia." (PMID 23823008, 2013). "Moreover, hypomorphic Sp4 mutant mice with reduced expression of the Sp4 gene displayed vacuolization in the hippocampus as well as deficits in sensorimotor gating and memory, putative endophenotypes for several psychiatric disorders including schizophrenia and bipolar disorder." (PMID 19401786, 2009). "By contrast, the non-DD/ID mutants (Akap11+/−, Dagla+/−, Gria3−/y, Sp4+/−) showed upregulation of these schizophrenia, NDD, and ASD gene sets in the thalamus." (PMID 41022686, 2025). "This study, together with previous findings showing that SP4 and SP1 control the expression of D2 receptor in the cerebellum in schizophrenia, suggests a possible role of the transcription factors SP1 and SP4 in this circuit from the cerebellum to prefrontal cortex." (PMID 38919799, 2024). "The present study concluded that Sp4 hypomorphic mice present as a novel hypoglutamatergic genetic model to mimicking reduced NMDAR1 expression and increased sensitivity to NMDAR antagonists in schizophrenia." (PMID 23823008, 2013).
breast carcinoma (11 papers, 1976 to 2025). "A previous study showed that TSPO expression is regulated by the binding of Sp1, Sp3 and/or Sp4 to the proximal promoter region in human breast cancer cell lines, and a similar sequence was observed in the mouse Tspo gene." (PMID 31536603, 2019). "Additionally, Tat-SP9 also showed more potent anti-proliferative efficacy than Tat-SP4 in ERBB2-POSITIVE breast cancer cells." (PMID 37958451, 2023). "Moreover, treatment of penfluridol with A549 cells did not inhibit or slightly enhanced the expression of Sp1, Sp3, and Sp4, suggesting the underlying mechanisms involved in the anticancer action of penfluridol in NSCLC and breast cancer are different." (PMID 31308361, 2019). "Immunization with irradiated rat embryo cells failed to influence the growth and development of tumour cells prepared from hepatoma D23 and D30, sarcoma Mc57, mammary carcinoma AAF57 or cells prepared from spontaneously arising mammary carcinomata Sp4 and Sp15." (PMID 181040, 1976). "Thus Tat-SP4 induced necrotic cell death in TNBC cells similar to HER2+ breast cancer cells." (PMID 37598181, 2023). "In this study, we collected breast cancer cells at 1st, 2nd, 3rd, and 4th which were numbered SP1, SP2, SP3 and SP4 in the spheroid formation experiment." (PMID 38037058, 2023). "Our previous studies showed that Tat-SP4 promoted endolysosomal degradation of EGFR and HER2, which are oncogenic drivers for non-small cell lung cancer (NSCLC) and HER2+ breast cancer subtype respectively." (PMID 37598181, 2023). "In our previous studies, Tat-SP4 showed moderate anti-proliferative efficacy in cell line models of non-small-cell lung cancer (NSCLC) and HER2+ breast cancer with IC50 values of ~30–50 μM." (PMID 36765914, 2023). "Overall, our data confirm that Tat-SP4 induced predominantly non-apoptotic cell death in PDAC cells similar to HER2+ breast cancer cells." (PMID 36765914, 2023). "Our previous study reported that Beclin 1-targeting stapled peptides, including Tat-SP4 and another similar peptide with (i, i + 4) linkage for the hydrocarbon staple induced non-apoptotic cell death in NSCLC, breast cancer cells and hepatocellular carcinoma (HCC) cells." (PMID 36765914, 2023).